HLA-G (major histocompatibility complex, class I, G)
Diseases named in the same sentence as HLA-G in open-access papers (continued):
Sharing a sentence is not in itself a finding about the gene and the disease.
cancer (continued). "Emphasizing the third point, HLA-G genetic variation affects its expression at the transcriptional and post-transcriptional level; for that, it is important to explore the association between its genetic determinants and cancer susceptibility and progression." (PMID 37623251, 2023). "Thus, HLA-G+ immune cells are probably implicated in the complex mechanisms underlying the pathogenesis of various disorders including infections, transplants, cancers, and immune-mediated diseases." (PMID 35204759, 2022). "In addition to alternative splicing of HLA-G transcripts, deletions, insertions and nucleotide polymorphisms of the HLA-G gene have been described, which are important parameters for cancer and clinical correlations." (PMID 35185904, 2022). "In this light, the study of genetic polymorphisms in HLA-G may become an interesting prognostic and predictive biomarker for cancer." (PMID 36559230, 2022). "Similar to other immune checkpoints, a higher expression of pro-inflammatory transcripts appears to be associated with a higher HLA-G expression in cancer, suggesting that HLA-G could be upregulated to counteract the host’s immune response." (PMID 34948104, 2021). "Among the HLA genes, HLA-G gene expression was found to be upregulated when cells develop malignant phenotype, and it is identified to be associated with cancer inflammation, expressed in both cancer cells and immune cells, especially in CD68+ macrophages and CD8+ T cells infiltrating cancer tissue." (PMID 34306024, 2021). "The aim of this review was to determine to what extent it is justified that HLA-G expression is considered as a target for immune checkpoint inhibiting therapy by critically assessing the association between HLA-G expression by carcinomas and clinical outcome of patients." (PMID 34361031, 2021). "Clinical studies involving diagnostic and prognostic significance of HLA-G in cancer." (PMID 33425752, 2020). "Notably, because polymorphism observed at non-coding regions of HLA-G can affect its expression pattern, it seems to be a genetic factor implicated in the cancer susceptibility." (PMID 33425752, 2020). "The relationship between the HLA-G 14 bp Ins/Del polymorphism and cancer risk was assessed." (PMID 30962267, 2019). "Therefore, we undertook a meta-analysis to assess the effects of the HLA-G 14-bp Ins/Del polymorphism on cancer risk." (PMID 30962267, 2019). "Previously, published meta-analyses also performed subgroup analysis to explore the association between the HLA-G 14 bp Ins/Del variant and risk of developing cancer; some significant results were reported and are partially in line with the conclusions from our present study." (PMID 30962267, 2019). "The results allowed us to hypothesise that the HLA–G 14-bp Ins/Del variant may be a potential protective factor of cancer." (PMID 30962267, 2019). "Furthermore, results from studies on the correlation between the HLA-G 14-bp Ins/Del polymorphism in the same types of cancer were inconsistent." (PMID 30962267, 2019). "Despite our efforts to assess the association between the HLA–G 14–bp Ins/Del variant and the risk of cancer, there are several limitations we must account for in the present meta-analysis that may impact the objectivity of the findings." (PMID 30962267, 2019). "Additionally, some 3′ untranslated region (3′UTR) single nucleotide polymorphisms (SNPs) of the HLA-G gene were found to be independently associated with cancer susceptibility and cancer prognosis." (PMID 28781970, 2017). "Previous studies have reported significant associations between HLAG polimorphisms (in particular the +2960 14-bp INDEL) and cancer risk, but to the best of our knowledge, this is the first study indicating a role for HLA-G 3’UTR regulatory SNPs in DFS and OS after adjuvant treatment of CRC." (PMID 26633805, 2015). "Additionally, there is an association between HLA-G and cancer." (PMID 40994800, 2025).
cancer (continued). "Different HLA-G isoforms might underlie the diverse functions in cancer immunotherapy." (PMID 35185887, 2022). "Because genetic polymorphisms observed in the HLA-G 3’UTR have been associated with the posttranscriptional control of HLA-G expression, this gene segment has been studied in autoimmune, chronic inflammatory and chronic infectious diseases, in allografting and in several types of cancer." (PMID 24204558, 2013). "Elevated HLA-G expression correlates with poor prognosis in various cancers, with a meta-analysis showing a Hazard Ratio for mortality of 2.09." (PMID 41800033, 2026). "Our findings are of great importance for clarifying the clinical relevance of HLA-G2/6 and HLA-G1/4/5 expression in other cancers and for advancing precision HLA-G-targeted cancer immunotherapy for patients with solid tumors." (PMID 41194925, 2025). "When cancers were grouped into early and advanced stages, HLA-G expression was observed in 5.6% (2 out of 18) of early-stage patients and 11.1% (4 out of 18) of advanced-stage patients." (PMID 41234446, 2025). "Motivated by this finding, researchers evaluated HLA-G expression and its clinical relevance in more than 30 types of different pathological cancers." (PMID 41181133, 2025). "The significance of prognostic stratification of biomarkers, including HLA-G, has been observed in various cancers." (PMID 41194925, 2025). "Although studies have generally revealed that HLA-G expression varies dramatically among studies and even within the same type of cancer." (PMID 41194925, 2025). "While most previous studies have focused on the cancer itself and aberrant HLA-G expression has been repeatedly observed in various malignant lesions, few studies have reported weak or absent HLA-G expression in peritumoral tissues (PTTs)." (PMID 41181133, 2025). "JNJ-78306358, a CD3 HLA-G-targeted bi-specific T cell engager was evaluated in a Phase I clinical trial (NCT04991740) enrolling 39 patients with various cancers." (PMID 39766165, 2024). "HLA-G in tumors promotes the immune-suppressive microenvironment, which results in cancer progression and poor prognosis." (PMID 39594832, 2024). "Another common mechanism used by cancer cells to evade the immune system is HLA-G expression, a molecule of the major histocompatibility complex (MHC), with immunosuppressive activity and restricted expression in healthy individuals." (PMID 38954689, 2024). "As HLA-G expression is upregulated in BC patients, HLA-G and its receptors represent potential targets for cancer immunotherapy." (PMID 39594832, 2024). "The expression pattern of HLA-G in cancers is highly heterogeneous, with an overall trend of increasing with disease progression, suggesting that HLA-G plays an important role in the development of malignancy tumors." (PMID 38310272, 2024). "HLA-G plays a key role in the cancer immunoediting mechanism, attenuating the elimination of tumoral cells." (PMID 39408976, 2024). "There are indications that soluble HLA-G is also released by cancer cells and, consequently, is detectable in the circulation of cancer patients." (PMID 38473890, 2024). "The use of the CRISPR/Cas9 method to edit HLA-G from these cancer cells has indeed succeeded in reversing the induction mediated by HLA-G in wild-type RCC7 cells, demonstrating the direct implication of HLA-G in the regulation of NCAM1 expression." (PMID 39358558, 2024). "In conclusion, owing to the heterogeneity of the tumors and the discrepancies in detection tools and reagents, studies regarding HLA-G expression in cancers have shown mixed results." (PMID 38310272, 2024). "Therapies targeting HLA-G are emerging as a promising area of clinical research, with preliminary success in certain cancers." (PMID 38310272, 2024). "The overexpression of HLA-G has been observed in a variety of cancers, including lung, breast, ovarian, renal, gastric and colorectal cancer as well as hematological malignancies." (PMID 38391781, 2024).
cancer (continued). "HLA-G stands out as a crucial next-generation immune checkpoint showing great promise for the benefit of cancer patients." (PMID 38310272, 2024). "This will help advance the potential of HLA-G as a predictive biomarker for early cancers from bench to bedside." (PMID 38310272, 2024). "In cancer, HLA-G is involved in the progression of primary tumors to the metastatic stage, followed by poor prognosis and overall survival." (PMID 38391781, 2024). "By exploring the specific functions of HLA-E, HLA-F, HLA-G, and HLA-H in various cancers, the authors aim to highlight their importance in the immune system’s interaction with tumors." (PMID 39766165, 2024). "The soluble form of HLA-G (sHLA-G) can also be detected in the supernatant of body fluids or malignant effusions from cancer patients." (PMID 39703498, 2024). "In h-UC-Muse cells, CD133 (a marker for ESCs, HSCs, NSCs, and cancer stem cells) and HLA-G (relevant to immunotolerance in the placenta) expression were as high as ~ 99%- and ~ 65%, respectively." (PMID 38992309, 2024). "The overexpression of ILT2 and ILT4 receptors was found in various cancers and was related to de novo expressions of HLA-G." (PMID 38391781, 2024). "In recent years, significant interest has been directed toward the interplay between HLA-G, immunoediting, and cancer." (PMID 39549048, 2024). "This review also addresses the advancement of HLA-G-based therapies in preclinical and clinical settings, with a focus on their clinical application in cancer." (PMID 38310272, 2024). "HLA-G146-154 is an HLA-G-derived peptide that activates peptide Cytotoxic T lymphocytes, which can serve as a potential agent of anti-cancer immunotherapy." (PMID 38384647, 2024). "Cancer cells sensitized by chemotherapy highly expressed their HLA-G, thus promoting better activation and cancer antigen recognition for CAR-NK cells." (PMID 38726000, 2024). "Chemotherapy upregulated HLA-G by inhibiting DNMT1 and inducing demethylation of TAP1, providing opportunities for anti-HLA-G CAR-NK cells to eliminate cancer cells." (PMID 38310272, 2024). "Here, to unravel potential roles of HLA-G in cancer cells, the RCC7 cell line derived from a ccRCC patient was used as model." (PMID 39358558, 2024). "This will provide further insight into the future clinical applications of HLA-G inhibition for the benefit of more cancer patients." (PMID 38310272, 2024). "What is the efficacy and safety of strategies targeting HLA-G as monotherapy or in combination with existing ICBs such as anti-PD-1/PD-L1 antibodies in the treatment of cancer?" (PMID 38310272, 2024). "ILT3 binds to a ligand called HLA-G, which has been shown to be expressed by cancer cells and is thought to contribute to its ability to evade the immune system." (PMID 38254772, 2024). "In order to develop a novel approach for cancer treatment, it is crucial to incorporate HLA-G antibodies together with antibodies that target immune checkpoints, such as PD-1, CTLA-4 and TIM-3." (PMID 38391781, 2024). "HLA-G was recently found to be highly expressed in some cancer types regulating immune escape from cytotoxic T cells." (PMID 36697401, 2023). "The expression of HLA-G on immune cells increases in disease conditions such as infection, cancer, and transplantation." (PMID 37627278, 2023). "On the other hand, cancer, autoimmune disease, viral infection, inflammation and transplantation can induce HLA-G expression." (PMID 37875821, 2023). "Enhanced expression of HLA-G contributes to the pathogenesis of viral infections and cancer by downregulating immune responses." (PMID 38022598, 2023). "Although the relevance of HLA-G in cancer incidence and development has been demonstrated, characterizing the pattern of this neo expression remains challenging due to the absence of antibodies against the less studied isoforms (HLA-G2, G3, G4, G6, and G7)." (PMID 38162657, 2023).
cancer (continued). "Remarkably, HLA-G is affiliated with multicellular sphere formation in cancer cells in vitro implying a role for HLA-G in cancer stem cells self-renewal." (PMID 36780531, 2023). "Under normal physiological conditions, the expression of HLA-G is restricted to immune-privileged organs, but it is upregulated in some immune-mediated diseases, such as viral infections and cancer." (PMID 36960057, 2023). "In the context of cancer, the immunoediting process includes the gain of expression of immune-inhibitory molecules such as HLA-G." (PMID 37623251, 2023). "Considerable attention has been devoted to the study of the inhibitory checkpoint human leukocyte antigen (HLA)-G in human cancers." (PMID 37569841, 2023). "HLA-G can also hinder the movement of different immune cells to the site of cancer growth, either by binding to or transferring receptors from the surface of the immune cells." (PMID 37048814, 2023). "The mechanisms that stimulate HLA-G expression in the context of cancer are complex, depending on the individual’s genetic background and various environmental factors such as hypoxia, stress, hormones, and specific cytokines." (PMID 37629044, 2023). "Many HLA molecules, for example, HLA-E, HLA-F, HLA-G, HLA-H and HLA-DR were reported to be overexpressed on cancer cells." (PMID 36778644, 2023). "HLA-G expression has been found to have diverse effects on malignancies, which include inhibiting the immune system’s ability to kill cancer cells, inducing immune cell death, and promoting the production of immune cells that regulate the immune response." (PMID 37048814, 2023). "Accordingly, these variation sites along the HLA-G gene have been reported in pre-eclampsia, cancer, transplants, and autoimmune, chronic inflammatory, and infectious disorders." (PMID 37629044, 2023). "HLA-G+ cancer cells can induce macrophages to polarize towards an M2 phenotype, characterized by the expression of SPP1 (osteopontin)." (PMID 38187388, 2023). "High HLA-G and SPAG9 expression has been independently linked to poor survival outcomes in lung and other cancers (49, –51)." (PMID 36780531, 2023). "Recent studies utilizing spatial transcriptomics and single-cell sequencing have shed light on the interaction between HLA-G+ cancer cells and SPP1+ macrophages in the immune microenvironment at the invasive front of CRC." (PMID 38187388, 2023). "Firstly, aberrant LILRB expression occurs in several human cancers but not healthy adjacent tissues, with the expression of LILRBs and HLA-G found to correlate with poorly differentiated, more advanced or aggressive cancers in most cases." (PMID 38022598, 2023). "Because of its immunosuppressive effects, HLA-G has been extensively studied for its role in cancer immunotherapy." (PMID 37103820, 2023). "Tumors often ectopically express HLA-G, and in vitro experiments have demonstrated that expression of HLA-G makes cancer cells more resistant to cytolysis and helps them to escape from immunosurveillance." (PMID 37974170, 2023). "In the context of pathological conditions, cancer represents one of the major focuses of interest, and the role of HLA-G has been widely analyzed and studied." (PMID 35328349, 2022). "Accumulating evidence has shown that HLA-G is an immune checkpoint molecule with specific relevance in cancer immune escape, although the role of HLA-G/KIR2DL4 in antitumor immunity is still uncharacterized." (PMID 35185887, 2022). "For instance, the up-regulation of HLA-G in tumors and the enhanced serum levels of soluble form have been identified in malignancies, probably leading to tumoral immune evasion and cancer progression due to their inhibitory actions on the immune system." (PMID 35204759, 2022). "Taken together, all these features highlight the role of HLA-G as an immune checkpoint (IC) molecule and as a novel therapeutic target for cancer immunotherapy, as recently discussed." (PMID 35328349, 2022).
cancer (continued). "The membranous HLA‐G is significantly expressed in cancers and plays a significant role in their diagnosis and progression." (PMID 35759240, 2022). "Human leukocyte antigen G (HLA-G) is an immune checkpoint molecule with relevance in several cancers." (PMID 36618382, 2022). "Clinical trials using monoclonal antibodies against HLA-G and other IC are currently ongoing with cancer patients where antibodies and inhibitors of PD-1 and CTLA-4 showed encouraging results." (PMID 35328349, 2022). "Based on these characteristics, HLA-G is postulated as a novel potential immune checkpoint in different malignancies raising the question how HLA-G expression influences existing cancer immunotherapies including checkpoint inhibitors?" (PMID 35185904, 2022). "Recent data in the literature indicate that HLA-G also plays an important role in liver homeostasis and immune response to liver injury and/or cancer." (PMID 36311782, 2022). "CTLA-4 represents one of the first IC studied that is neo-expressed in many adult and pediatric cancers or with increased expression in different tumors, mostly correlated with HLA-G and PD-L1/L2." (PMID 35328349, 2022). "In the present study, the HLA-G-driven DEG signature suggested a great predictive ability in the OS of cancer patients." (PMID 35924232, 2022). "In this context, immunoregulatory molecules, like HLA-G, play an important role in the progression of cancer." (PMID 35154112, 2022). "The current evidence supports that HLA‐G is involved in cancer; however, discrepancies related to cancer heterogeneity and differences in methods remain." (PMID 35759240, 2022). "Selective HLA-G expression allows not only viruses, but also cancer cells, to escape from immune host control and elimination." (PMID 36010256, 2022). "Although HLA-G is not physiologically expressed in most adult tissues, neoexpression/(re)expression of HLA-G is a frequently observed phenomenon in different cancers thereby inducing an immunological tolerance and suppression of immune surveillance." (PMID 35185904, 2022). "In fact, over the years, many studies have reported on the expression of HLA-G in many different types of cancers, which supports the idea that this molecule participates in cancer development." (PMID 35154112, 2022). "As mentioned, in addition to genetic studies, determination of HLA-G expression is key to understanding the involvement of this molecule in cancer." (PMID 35154112, 2022). "Malignant neoplasms use various mechanisms to escape from the host’s immune control; the wide range of HLA-G activity suggests that it plays an important tolerogenic role in this process." (PMID 36010256, 2022). "Though development of HLA-G/ILTs interaction targeted ICIs is promising for cancer immunotherapy, much real-world information on HLA-G/ILTs status is extremely necessary for both future basic and clinical investigations." (PMID 34276691, 2021). "In the serum of healthy people, the content of HLAG is 20 ng/mL and significantly lower compared with cancer patients." (PMID 34868081, 2021). "Of note, COL4A1 and HLA-G were screened as hub ligands in the TAM-cancer stem cell (CSC) interactions." (PMID 33971970, 2021). "Upregulation of HLA-G in cancer contributes to serious immunosuppression, because besides inhibiting NK cell cytotoxicity, proliferation and transendothelial migration, it also inhibits the functions of cytolytic T cells, B cells and dendritic cells." (PMID 34206399, 2021). "The abnormal expression of HLA-G on malignant tumors has been found to correlate with a high invasive or metastatic status and poor clinical outcome." (PMID 33422072, 2021). "This is in line with results from other groups showing that estrogen can activate HIF-1α and that activation of HIF-1α stimulated HLA-G-expression in cancer cells." (PMID 35111157, 2021). "PD-L1+HLA-G+ cancer cells were enriched in IT immune cold samples, while depleted from IT immune excluded samples." (PMID 34215851, 2021).